AURKB (aurora kinase B)
Diseases named in the same sentence as AURKB in open-access papers (continued):
Sharing a sentence is not in itself a finding about the gene and the disease.
medulloblastoma (3 papers, 2011 to 2023). A malignant, invasive embryonal neoplasm arising from the cerebellum. "The specific inhibition of Aurora kinase B was achieved in MYC-overexpressing medulloblastoma cells with AZD1152-HQPA." (PMID 25739120, 2015). "Our results suggest the potential for therapeutic application of Aurora kinase B inhibitors in the treatment of Group 3 medulloblastoma." (PMID 25739120, 2015). "One of the key regulatory kinases involved in multiple stages of mitosis is Aurora kinase B. We hypothesized that medulloblastoma cells that overexpress MYC would be uniquely sensitized to the apoptotic effects of Aurora B inhibition." (PMID 25739120, 2015).
sarcoma (3 papers, 2019 to 2021). A usually aggressive malignant neoplasm of the soft tissue or bone. "We then confirmed the heterogeneous expression of AURKA and AURKB in nine sarcoma cell lines, both at genomic and protein levels." (PMID 32138169, 2020). "Recently, a dual inhibition of AURKA and AURKB shown efficiency on several cancer cell lines, including sarcomas and a promising Phase II study was done on metastatic sarcomas." (PMID 32138169, 2020). "CDK1, KIF11, AURKB, MAD2L1, BUB1B and CCNB2 were highly expressed in sarcoma and were markedly related to worse OS." (PMID 34838000, 2021). "We report in this work the effect of AURKA and AURKB inhibition by AMG 900, doxorubicin or both in different sarcoma cell lines, focusing on 4 dedifferentiated liposarcomas." (PMID 32138169, 2020). "Amongst the eight remaining hub genes, CDC20, CCNB2, AURKB, MAD2L1, CENPE, KIF2C, and PCNA were highly expressed and related with negative prognosis of sarcoma." (PMID 31870357, 2019).
squamous cell carcinoma (3 papers, 2020 to 2022). A carcinoma arising from squamous epithelial cells. "Likewise, AURKB was found to be induced in the squamous carcinoma subtype of NSCLC and the expression level of AURKB also served as a marker for resistance to paclitaxel, a drug commonly used in the treatment of NSCLC." (PMID 33915740, 2021). "Among these, MMP12, AURKB, SERPINE1, and MMP1 have been confirmed to play important roles in squamous cell carcinoma including LSCC." (PMID 33680908, 2020).
anaplastic thyroid carcinoma (2 papers, 2020). "Elevated expression of AURKB in thyroid anaplastic carcinoma cells can induce higher growth rate, and inhibition of AURKB expression by RNA interference has resulted in reduced proliferation of these cells." (PMID 32761869, 2020).
breast invasive ductal carcinoma (2 papers, 2022 to 2024). "First, we analyzed the mRNA levels of AURKB in prostate adenocarcinoma patients and breast invasive ductal carcinoma patients with low mRNA levels of BRCA2 from cBioPortal." (PMID 37934606, 2024).
chondrosarcoma (2 papers, 2012 to 2024). A malignant cartilaginous matrix-producing mesenchymal neoplasm arising from the bone and soft tissue. "The positive ratio of Aurora Kinase B was 65.3% (47/72) in the chondrosarcoma and 19% (8/42) in the chondroma tissues." (PMID 22809428, 2012). "The positive ratio of Aurora Kinase B was significantly higher in the chondrosarcoma than that in chondroma tissues (p<0.01)." (PMID 22809428, 2012). "In the future, our group will study whether Aurora Kinase B inhibitors can inhibit the growth and proliferation of chondrosarcoma cells in vitro and in vivo." (PMID 22809428, 2012). "Moreover, we found the positive expression of Aurora Kinase B was significant different between the metastatic group and non-metastatic group and the recurrence group and the non-recurrence group, which suggests that Aurora Kinase B impacts on the invasiveness of chondrosarcoma." (PMID 22809428, 2012).
Diabetic Nephropathy (2 papers, 2022 to 2025). "Several research studies have highlighted the association between Aurora kinase B (AURKB) and diabetic nephropathy." (PMID 40059874, 2025).
diffuse large B-cell lymphoma (2 papers, 2023 to 2024). "The active pharmaceutical ingredient in AZD2811 (AZD1152) has previously undergone clinical evaluation for diffuse large B-cell lymphoma (DLBCL), and the combination activity of aurora kinase B inhibitors and BH3 mimetics has been investigated in solid and hematologic malignancies." (PMID 38456804, 2024).
gestational diabetes (2 papers, 2022 to 2025). Carbohydrate intolerance first diagnosed during pregnancy. "Taken together, these results suggest that high levels of AURKB expression could play a role in causing trophoblast dysfunction in gestational diabetes." (PMID 40059874, 2025). "The findings from RT-qPCR and western blotting show that when in a high-glucose environment, AURKB expression increases in both the placenta and trophoblast cells of patients with gestational diabetes mellitus." (PMID 40059874, 2025). "Based on findings from gene co-expression network analysis, AURKB has the potential to serve as a valuable biomarker for gestational diabetes." (PMID 40059874, 2025). "This research investigates how Aurora kinase B (AURKB) functions in trophoblast cells when they are exposed to high levels of glucose during gestational diabetes." (PMID 40059874, 2025). "A study of gene coexpression network analysis identified that AURKB might be valuable biomarkers of gestational diabetes mellitus." (PMID 35222021, 2022). "However, the role and mechanism of AURKB in gestational diabetes are rarely reported." (PMID 40059874, 2025). "We then used serum from women with gestational diabetes and trophoblast cells grown in high-glucose conditions to perform RT-qPCR and western blotting experiments, which confirmed Zhao’s previous research by showing that HG levels increased the expression of AURKB." (PMID 40059874, 2025).
HIV-1 infection (2 papers, 2022 to 2023). The type species of lentivirus and the etiologic agent of acquired immunodeficiency syndrome (AIDS). "Thus, the CTD of HIV-1 envelope mediates AURKB relocalization to nuclear puncta, in correlation with AURKB effects on HIV-1 infection spread." (PMID 37459363, 2023). "How this early increase in AURKA and AURKB activity may contribute to HIV-1 infection remains to be determined." (PMID 37459363, 2023). "In this sense, a recent investigation showed that epigenetic changes in aurora kinase B (AURKB) and aurora kinase C (AURKC) are involved during the early stages of HIV-1 infection." (PMID 35628408, 2022). "Thus, while HIV-1 infection increases AURKA and AURKB levels in newly infected cells, later cell-cell interactions and Env signaling appear to function to counter undesirable AURKB activity at the plasma membrane that would otherwise inhibit Env fusogenicity and HIV-1 spread." (PMID 37459363, 2023).
malignant mesothelioma (2 papers, 2017 to 2020). A malignant neoplasm of the pleura or peritoneum, arising from mesothelial cells. "AURKB was detected over-expressed in pleomorphic gliomas, malignant mesothelioma, and hematological malignancies." (PMID 32194417, 2020).
mesothelioma (2 papers, 2014 to 2020). A usually malignant and aggressive neoplasm of the mesothelium which is often associated with exposure to asbestos. "Likewise, ZM447439, an Aurora kinase inhibitor, has shown effective inhibition of both AURKA and AURKB activities via reduction in histone H3 phosphorylation, resulting in decreased cell growth in mesothelioma cell lines." (PMID 33202573, 2020). "In another study, microarray analyses of pleural mesotheliomas revealed that the more aggressive mesotheliomas expressed increased levels of AURKA and AURKB and functionally related genes involved in cell cycle control and mitosis." (PMID 33202573, 2020). "In human mesothelioma tissues, Crispi’s group found upregulated levels of AURKA and related genes as well as increased amounts of both AURKA and AURKB in five mesothelioma cell lines indicating a potential involvement of Aurora kinases in the oncogenesis of MPM." (PMID 33202573, 2020).
metastatic disease (2 papers, 2014 to 2018). "It is necessary to underline that although mutated ERBB2, PTPRT, PTPRD and AURKB predicted poor OS in univariate analysis they were excluded from the multivariate analysis because they were preferentially identified in patients with late stage (stage III-IV) and/or metastatic disease." (PMID 29844865, 2018).
myelodysplastic syndrome (2 papers, 2018 to 2022). A clonal hematopoietic disorder characterized by dysplasia and ineffective hematopoiesis in one or more of the hematopoietic cell lines. "Few years ago, we have demonstrated that AURKA and AURKB overexpression were associated with genomic instability in cytogenetically stratified group (Normal vs. Abnormal karyotype) of hematopoietic cells and bone marrow derived mesenchymal stem cells (MSCs) of myelodysplastic syndrome patients." (PMID 36175852, 2022).
myeloid leukaemia (2 papers, 2020 to 2021). "To assess the potential effect of the AURKB/C inhibitor GSK1070916 on myeloid leukaemia metastases in human ovarian tissue, we first used Western blot analysis to examine AURKB and AURKC expression levels in a panel of six myeloid leukaemia cell lines and in human ovarian cortex." (PMID 33725274, 2021).
oral squamous cell carcinoma (2 papers, 2015 to 2021). "Aurora kinase B protein levels are positively correlated with cancer cell proliferation and tumor progression in human oral squamous cell carcinomas." (PMID 26110572, 2015).
pulmonary fibrosis (2 papers, 2020 to 2024). Chronic progressive interstitial lung disorder characterized by the replacement of the lung tissue by connective tissue, leading to progressive dyspnea, respiratory failure, or right heart failure. "AURKB promotes the proliferation and survival of fibroblasts, and thus, inhibition of AURKB attenuates fibroblast activation and lung fibrosis." (PMID 38343538, 2024). "We identified a role for WT1 in AURKB expression and AURKB‐driven transcripts involved in proliferation and survival of fibroblasts in the pathogenesis of pulmonary fibrosis." (PMID 32761869, 2020). "Our preclinical study describes the pathological role for AURKB in fibroblast activation and presents a potential therapy for the treatment of pulmonary fibrosis using barasertib." (PMID 32761869, 2020). "In summary, we have identified and described the pathological role for AURKB in fibroblast activation and pulmonary fibrosis." (PMID 32761869, 2020). "We show that fibrosis induced by TGFα is highly dependent on AURKB expression and treating TGFα mice with barasertib, an AURKB inhibitor, reverses fibroblast activation, and pulmonary fibrosis." (PMID 32761869, 2020). "We evaluated the in vivo effects of AURKB inhibition by barasertib using mouse models of TGFα‐ and bleomycin‐induced pulmonary fibrosis." (PMID 32761869, 2020). "However, future studies are needed to evaluate possible binding partners and other molecular regulators downstream of WT1 and AURKB in fibroblast activation and pulmonary fibrosis." (PMID 32761869, 2020). "To substantiate our hypothesis that AURKB inhibition with barasertib attenuates pulmonary fibrosis, we used an alternative mouse model of bleomycin‐induced pulmonary fibrosis." (PMID 32761869, 2020). "In vivo studies using the TGFα‐ and bleomycin‐induced mouse models of pulmonary fibrosis demonstrate that barasertib, a known AURKB inhibitor, attenuates fibroproliferation, myofibroblast survival, and ECM deposition in established and ongoing pulmonary fibrosis." (PMID 32761869, 2020). "AURKB, also known as Aurora kinase B, is upregulated in fibroblasts from IPF patients and in lung tissues of TGF-α and BLM-induced pulmonary fibrosis." (PMID 38343538, 2024). "Here, we show for the first time that AURKB is upregulated in fibroblasts of IPF and a mouse models of pulmonary fibrosis." (PMID 32761869, 2020). "Compared to control siRNA, knockdown of WT1 was sufficient to attenuate the expression of AURKB in lung fibroblasts isolated from both IPF and a mouse model of TGFα‐induced pulmonary fibrosis." (PMID 32761869, 2020). "Our results demonstrate that AURKB is upregulated in fibroblasts isolated from fibrotic lung lesions of IPF and a mouse model of TGFα‐induced pulmonary fibrosis." (PMID 32761869, 2020).
renal carcinoma (2 papers, 2020). A carcinoma arising from the epithelium of the renal parenchyma or the renal pelvis. "To investigate the mechanism of AURKB on the development of renal cancer, then we detected the biological function of AURKB." (PMID 32194783, 2020). "Additionally, the previous studies also showed AURKB might be a proliferation-independent prognostic factor in breast and renal cancers." (PMID 32863956, 2020).
retinoblastoma (2 papers, 2021 to 2024). A malignant tumor that originates in the nuclear layer of the retina. "In our recent study, we showed enrichment of a MYCN binding motif on the promoter of AURKB in human retinoblastoma and that supports a direct regulation of AURKB by MYCN." (PMID 33915740, 2021). "Recently, we have shown that AURKB is overexpressed in retinoblastoma compared to adjacent healthy retina and its expression significantly correlated with histological risk factors such as optic nerve and anterior chamber invasion." (PMID 33915740, 2021). "Recent investigations have also demonstrated that AURKB is overexpressed in retinoblastoma compared to neighbouring healthy retinas, and its expression correlates significantly with histological risk factors including invasion of the optic nerve and anterior chamber." (PMID 38898693, 2024).
asthma (1 paper, 2019). "GSEA indicated that genes involved in autoimmune thyroid disease, intestinal immune network for IgA production, antigen processing and presentation, cytokine-cytokine receptor interaction, asthma, etc., were differentially enriched in the AURKB high expression phenotype." (PMID 31576249, 2019).
bladder urothelial carcinoma (1 paper, 2019). "Finally, on the Aurora kinase gene AURKB (rs101079278) a close mutation was reported on bladder urothelial carcinoma (AURKB S37Y)." (PMID 31438887, 2019).
Burkitt lymphoma (1 paper, 2024). A rare form of malignant mature B-cell non-Hodgkin lymphoma. "Through re-analysis of the RNA seq data using SKN-BE2 and Burkitt’s lymphoma Ramos cells with or without USP29 depletion (GSE180797), we revealed that USP29 depletion resulted in significant downregulation of AURKB pathway." (PMID 38233848, 2024).
cholangiocarcinoma (1 paper, 2023). A carcinoma that arises from the intrahepatic biliary tree (intrahepatic cholangiocarcinoma) or from the junction, or adjacent to the junction, of the right and left hepatic ducts (hilar cholangiocarcinoma). "In the present study, it observed that the protein and mRNA levels of AURKB were high expression in cholangiocarcinoma cells with high metastasis potential (HCCC9810) and low expression in cholangiocarcinoma cells with low metastasis potential (RBE and Huh28)." (PMID 37318676, 2023).
cyst (1 paper, 2024). A sac-like closed membranous structure that may be empty or contain fluid or amorphous material. "In contrast, Inpp5eΔ/Δ;AurkaΔ/Δ Alisertib-treated mice displayed no change in kidney-to-body-weight ratio, cyst index, cyst number or cyst size, confirming Alisertib requires AURKA (and not AURKB or other targets) to elicit these pro-cystogenic effects." (PMID 38191531, 2024).
desmoplastic small round cell tumor (1 paper, 2015). Desmoplastic small round cell tumor (DSRCT) is an aggressive soft tissue cancer that typically arises in serous lined surfaces of the abdominal or pelvic peritoneum, and spreads to the omentum, lymph nodes and hematogenously disseminates especially to the liver. "One patient with desmoplastic small round cell tumor (DSRCT) harbored the novel AURKB and MCL1 gene amplifications." (PMID 25859559, 2015).
embryonal cancer (1 paper, 2016). A non-seminomatous malignant germ cell tumor characterized by the presence of large germ cells with abundant cytoplasm resembling epithelial cells, geographic necrosis, high mitotic activity, and pseudoglandular and pseudopapillary structures formation. "Meanwhile, MAD2L1 and AURKB were involved in DO terms of type cancer, germ cell cancer, embryoma, and embryonal cancer." (PMID 27610375, 2016).
gliomas of the brain (1 paper, 2022). "AURKB may help gliomas of the brain become resistant to chemotherapy." (PMID 35774141, 2022).
head and neck cancer (1 paper, 2023). A primary or metastatic malignant neoplasm affecting the head and neck. "Our study suggests that KDM5D regulates persister head and neck cancer cells by modulating AURKB expression." (PMID 36982384, 2023).
hepatoblastoma (1 paper, 2020). Hepatoblastoma (HB) is a malignant hepatic tumor and is the most common pediatric liver cancer. "Interestingly, other investigators have identified a LIN28B-RAN-AURKA signaling axis in hepatoblastoma and have defined Aurora kinase B (AURKB) as a molecular target of LIN28b/let-7 signaling." (PMID 32923517, 2020).
Hyperinsulinemia (1 paper, 2024). An increased concentration of insulin in the blood. "Additionally, hyperinsulinemia inhibited the transcriptome required for cell cohesion MELK, CDCA7, ESCO2, mitotic spindle assembly KIF15, SGO1, and AURKB, and kinetochore formation KNL and NDC80." (PMID 39768214, 2024).
immune thrombocytopenia (1 paper, 2022). "Bosutinib is an inhibitor of CDK2 for chronic granulomatous leukemia treatment, and fostamatinib is an inhibitor of AURKB for persistent/chronic adult immune thrombocytopenia treatment." (PMID 36105485, 2022).
leukoplakia (1 paper, 2024). A white patch or plaque on a mucous membrane that cannot be characterized clinically or pathologically as any other disease. "During the progression from leukoplakia to HNSCC, we found several prognostic cell subgroups, such as AURKB + epithelial cells, SFRP1 + fibroblasts, SLC7A8 + macrophages, FCER1A + CD1C + dendritic cells, and TRGC2 + NK/T cells." (PMID 38582791, 2024).
mental retardation syndrome X-linked (1 paper, 2022). "AT-rich interactive domain 1A (ARID1A), aurora kinase B (Aurora-B), α-thalassemia/mental retardation syndrome X-linked (ATRX), and baculoviral IAP repeat-containing 5 (BIRC5) are also among the genes involved in cancer drug resistance." (PMID 35715750, 2022).
metastatic melanoma (1 paper, 2021). A melanoma that has spread from its primary site to another anatomic site. "Increased expression levels of AURKA or AURKB are significantly correlated with poor patient survival in metastatic melanoma patients." (PMID 33123754, 2021).
neuropathy (1 paper, 2024). A disorder affecting the nervous system that manifests with pain, tingling, numbness, and/or muscle weakness. "Specific genes increased in patients withoutlinezolid-associated neuropathy included ATG4C, BAX, and IGF1, while patients onlinezolid who suffered from neuropathy had an increase in AURKB, CASP3, CASP8, CDK1,CDKN1B, CEBPB, NADSYN1, NRF1, GPX7, and SBSN." (PMID 38939039, 2024).
nevus (1 paper, 2021). Nevus (or naevus, plural nevi or naevi, from nævus, Latin for "birthmark") is the medical term for sharply circumscribed[1] and chronic lesions of the skin or mucosa. "Transduction of nevus melanocytes with an AURKB and mCherry expressing lentiviral vector at low multiplicity of infection showed that the mCherry positive cells divided significantly more than their mCherry negative counterparts in cells from all three nevus donors." (PMID 34812139, 2021).